LEP (leptin)
Diseases named in the same sentence as LEP in open-access papers (continued):
Sharing a sentence is not in itself a finding about the gene and the disease.
Obesity (continued). "In our work, MS-induced obesity may lead to leptin signaling dysfunction, consequently, leptin resistance to food intake and body weight control." (PMID 36991247, 2023). "Collectively, these data indicated that, in Mc4r-KO mice — a model of hyperphagic obesity without leptin deficiency in which hepatic DNL is increased to a lesser extent than in ob/ob mice — hepatic FASN deficiency ameliorated both NAFLD and diabetes." (PMID 37681411, 2023). "The early onset of severe obesity, hyperphagia, persistent diarrhea, and metabolic abnormalities may be linked to mutations in the gene SRC-1, that inhibit the leptin-induced synthesis of POMC." (PMID 37512517, 2023). "As a link between obesity and OA, the use of leptin might be a potential approach for therapy in bone and joint diseases, especially for obese patients." (PMID 37024929, 2023). "Although the increase in CRP and plasma leptin concentration has been observed in obesity, it is unclear whether elevation in CRP is due to acute inflammation, adipose tissue expansion, or both." (PMID 36771307, 2023). "Studies have shown that POMC-specific deletion of Src1, a co-activator that enhances pSTAT3 transcriptional activity following leptin treatment, causes hyperphagia and obesity only when mice are fed with a HFD but not chow diet." (PMID 38027481, 2023). "The second ROC analysis with the composite endpoint diabetes and obesity showed, in addition to HgA1c, leptin, and visceral fat may have a role in the diagnosis of diabetes among obese adults." (PMID 36901837, 2023). "Utilizing biochemical criteria, such as measuring serum leptin, could have added more clarity to the evaluation of obesity." (PMID 37581135, 2023). "Elevated serum leptin in the presence of obesity could be a marker of reduced leptin sensitivity and may contribute to the obesity phenotype of KAEKI mice." (PMID 39916931, 2023). "In this context, it is tenable that the hyperactivation of sympathetic nerves in the liver and ovaries, induced by leptin excess during obesity, could be part of the pathogenesis of NAFLD and PCOS." (PMID 38069231, 2023). "Hence, our study investigated the potential effect of Zn supplementation on the cognitive biomarkers and leptin signaling pathway in high fat diet (HFD)-induced obesity rat model." (PMID 36977735, 2023). "This sex-dependent regulation of leptin may contribute to the sexual dimorphisms in obesity and cognition, however, this requires further investigation." (PMID 37086380, 2023). "Moreover, leptin levels are elevated in most individuals with obesity, suggesting leptin resistance." (PMID 37386040, 2023). "Apart from its correlations with obesity, it’s also believed that leptin could serve as a regulator of satiety mediated by GPCR in hypothalamus." (PMID 38017461, 2023). "Several studies have shown that dysfunctional adipose tissues secret adipocytokines, such as leptin, and subsequently promote adipose tissue and systemic inflammation, which is considered to be responsible for many obesity-related complications, including cancer." (PMID 37650871, 2023). "Moreover, this study aims to conduct a critical appraisal of existing literature that shows the connection between obesity and dementia via leptin and adiponectin." (PMID 37363537, 2023). "Dysfunction of leptin signaling and reduced adiponectin levels may contribute to the development of obesity." (PMID 37854354, 2023). "With the purpose to quantify adipokine secretion activity in each patient and its correlation with the development of the meta-inflammation seen in obesity, we measured the ratio beetween absolute blood leptin values and visceral adiposity area (leptin/VAT ratio)." (PMID 37668709, 2023). "Moreover, the NRG‐1/ErbB pathway enhances leptin levels, enlightening the possible approach of exploring underlying mechanisms of action of NRG‐1 in a myocardial IR model with obesity or a high‐fat diet." (PMID 37710187, 2023).
Obesity (continued). "There is a close relationship between obesity and leptin resistance, which may precede or co-occur with T2DM." (PMID 36674935, 2023). "Also, we found that diet-induced obesity leads to an increase in leptin levels while inducing an increase in norepinephrine levels in the liver and ovaries." (PMID 38069231, 2023). "Dysregulation of PVAT as a consequence of obesity leads to dysregulated production of adipokines and cytokines such as decreased hydrogen sulphide, NO, and adiponectin and increased leptin, IL-6, TNF-α, IL-12, hydrogen peroxide, and the renin–angiotensin–aldosterone system." (PMID 37372025, 2023). "A key result of our research was that we detected cut-off values for leptin and insulin, which may potentially be additional predictors of insulin resistance and obesity." (PMID 37373485, 2023). "However, mice with HFD-induced obesity exhibited leptin resistance, demonstrating the vicious pathology linking obesity and metabolic syndrome." (PMID 37371606, 2023). "Additional mechanisms of the carob-induced rise of HDL-C explained by our study could be due to the observed decrease in leptin levels and anti-obesity effects." (PMID 38004588, 2023). "In that regard, a narrative review suggested that leptin might be a therapeutic target potentiating prefrontal activity when individuals with obesity are exposed to food." (PMID 37261609, 2023). "However, in order to test new scientific approaches in human clinical trials breaking through the putative resistance of endogenous leptin in obesity, the mechanisms of action and signalling pathways of leptin remain to be fully determined." (PMID 37239098, 2023). "At hormonal levels—in line with the current literature—patients affected by OW and stages I–II of obesity demonstrated a progressive increase in leptin and insulin and a reduction in ghrelin, possibly impacting the imbalance of the taste signaling and food reward." (PMID 36904115, 2023). "Furthermore, inflammatory mediators and insulin-related signaling proteins, such as leptin and resistin, have been postulated to contribute to delayed wound healing in the setting of obesity." (PMID 36983872, 2023). "Obesity is induced by an imbalance between food intake and energy expenditure, both of which are tightly controlled by the CNS and influenced by peripheral hormones such as leptin." (PMID 38027481, 2023). "Leptin is associated with the initiation and promotion of EMT in breast, gastric, lung, ovarian, endometrial and oesophageal adenocarcinoma, particularly in obesity." (PMID 37233716, 2023). "Thereby, an individual with depression may present with obesity due to disturbed sleep patterns, a state that has been characterized as “leptin resistance”." (PMID 36832413, 2023). "Leptin resistance, decreased production of leptin and bicarbonate retention, and resetting of chemosensitivity during nocturnal periodic breathing contribute to the reduced ventilatory response to hypercapnia and/or hypoxia (typical in obesity)." (PMID 37763056, 2023). "In addition, leptin, an anti-obesity hormone, improves wound repairing by accelerating angiogenesis and promoting the proliferation, differentiation and migration of keratinocytes." (PMID 36983872, 2023). "Our data are strongly supported by an elegant study from Harvard Medical School, which clearly shows the anti-obesity and anti-diabetic properties of withaferin A through its leptin sensitizing action, and it may also impact the appetite of the animal." (PMID 36909161, 2023). "In obesity, the increased leptin levels may desensitize the GnRH neurons to leptin’s regulatory effects, leading to a dysregulation in the release of GnRH." (PMID 38264286, 2023). "The phosphorylation of HSL is activated by sympathetic nerve inputs, whereas HJGE may lower sympathetic tones by alleviating obesity and a paucity of leptin action." (PMID 37251332, 2023).
Obesity (continued). "Moreover, in the context of obesity, elevated leptin levels promote the attraction of monocytes and macrophages to blood vessels, producing inflammatory and adhesion molecules." (PMID 37821960, 2023). "The mislocalization of LepRb underlies leptin resistance and is sufficient to induce obesity as demonstrated by significant weight gain in mice lacking BBS1 in neurons expressing LepRb." (PMID 37064917, 2023). "Therefore, preliminary monitoring of leptin resistance is necessary to evaluate the effect of biogenic amines on obesity and NAFLD development." (PMID 36899958, 2023). "Interestingly, the obesity-related factors insulin and leptin have been reported to induce an increase in the expression of PLK1." (PMID 37447165, 2023). "Additionally, targeting inflammation in the adipose tissue or the hypothalamus introduces new possibilities to prevent diet-induced obesity as well as insulin and leptin resistance." (PMID 37957462, 2023). "The obesity phenotype of EF females suggested abnormalities in energy balance that might be a consequence of altered programming of the leptin-melanocortin system, as previously shown for their Dio3-/- fathers." (PMID 37560296, 2023). "Overall, the study concluded that heterozygous variants involving PCSK1, POMC, LEP, and LEPR are common among adult patients with class III obesity and occasionally may exhibit a phenotype similar to that of homozygotes." (PMID 37835041, 2023). "Preexisting obesity increases the concentration of leptin and resistin in the serum of pregnant women, which may be caused by the increased volume of adipose tissue." (PMID 37432262, 2023). "Leptin, as an inflammatory cytokine produced by visceral adipose tissue, could amplify systemic inflammation in COVID-19 patients with obesity." (PMID 37240656, 2023). "We subsequently demonstrated that targeted leptin supplementation without over-nutrition can normalize the neurodevelopment of the leptin-deficient mice without evoking obesity or adult hypertension." (PMID 37111184, 2023). "Additionally, patients with type 2 diabetes mellitus scored a higher percentage of hypertension, obesity, metabolic syndrome, and endothelial dysfunction if they had elevated leptin levels." (PMID 36901837, 2023). "The serum level of leptin is elevated paradoxically in obesity, and this high level of leptin may induce leptin resistance and result in altered glucose metabolism and insulin resistance." (PMID 36901837, 2023). "In addition, the effect of serum leptin concentration and leptin receptor expression on clinical and pathological parameters such as BMI, obesity, TNM, and tumor size was assessed." (PMID 36981858, 2023). "Limitations of the study include the fact that measurements of plasma insulin, cortisol, melatonin, and leptin could have elucidated some information on the variations of the prevalence of obesity in both girls and boys." (PMID 37508610, 2023). "Moreover, it was also found that the genetic imposition of diminished ER capacity leads to severe leptin resistance and obesity development." (PMID 38001815, 2023). "Both ISM1 and leptin seem to be expressed mainly by scWAT, increasing their levels in obesity." (PMID 38066623, 2023). "People living with obesity have elevated levels of the peptide hormone leptin." (PMID 37878001, 2023). "This suggests that periodic fasting may be beneficial to those with obesity, in terms of reducing leptin levels." (PMID 37049602, 2023). "Furthermore, hypothalamic SIRT-1 over-expression can control food intake and BW gain through increased leptin sensitivity in obesity." (PMID 36991247, 2023). "Flawed leptin transport to the CNS plays a major role in obesity development." (PMID 38089973, 2023). "Therefore, in the same study we directly compared the effects of leptin treatment and increased loading on body weight and body fat mass in lean mice and mice with diet-induced obesity." (PMID 37661748, 2023).
Obesity (continued). "Obesity cases demonstrated higher level of leptin than that in normal controls, indicating that obesity may be a leptin resistance condition." (PMID 36914629, 2023). "Although the exact mechanisms remain to be elucidated, obesity-related hormonal changes including leptin and insulin resistance are speculated to contribute to early puberty." (PMID 36947549, 2023). "However, in the case of pregnant women with obesity, leptin concentrations are higher throughout pregnancy compared to normal-weight women." (PMID 37834125, 2023). "Importantly, aberrations of both insulin and leptin signal transduction are implicated in serious metabolic disorders such as type 2 diabetes (T2DM) and obesity." (PMID 37298571, 2023). "In women, independent of obesity, the leptin-reducing allele increased height and decreased FPI, the cholestasis parameter gGT and the cytokine IL-6." (PMID 36833305, 2023). "Leptin is secreted by adipocytes and strongly inhibits feeding and increased energy expenditure mainly through receptors in the hypothalamus, and its inaction is thought to be important in the etiology of obesity." (PMID 36979821, 2023). "In addition, a marked increase in leptin has been found in obese individuals, especially in those with the coexistence of psoriasis and obesity." (PMID 36675592, 2023). "Not surprisingly, the obesity phenotype in EF females was associated with a higher level of serum leptin, and with increased WAT expression of Lep and Mest, two well-established markers of adipose tissue expansion." (PMID 37560296, 2023). "Therefore, by expressing adipocytokines such as leptin or adiponectin, adipose tissue plays a key role in the regulatory cascades involved in obesity and Metabolic Syndrome (MetS) and in the cross-talk between major organs (brain-HPT, liver, muscles)." (PMID 36837766, 2023). "The proportion of leptin and ghrelin levels, hormones that play a crucial role in the central control of appetite and energy expenditure, has been reported as a pathophysiological mechanism that links short sleep duration to obesity." (PMID 37403885, 2023). "Furthermore, poor glucose clearance in CKD, complications of dialysis, obesity, increased leptin: adiponectin ratio, vitamin difference and chronic inflammation all lead to insulin resistance." (PMID 37371050, 2023). "However, the hormonal milieu in obesity also contributes to LV hypertrophy, with insulin and leptin both stimulating myocyte hypertrophy." (PMID 36761185, 2023). "Multiple studies have observed that Leptin plays an important role in the development of obesity." (PMID 37705071, 2023). "Moreover, ongoing research is investigating molecules that counteract leptin resistance, a prevalent issue in obesity." (PMID 38264286, 2023). "Thus, circulating leptin interlinks obesity and inflammation, serving as a critical marker for inflammatory immune-mediated conditions including SLE." (PMID 37006245, 2023). "An important consideration for the development of therapeutic LepR agonists is that the serum levels of endogenous leptin are highly elevated in the context of human obesity, ranging from 5 ng/ml (0.3 nM) in lean individuals to as high as 100 ng/ml (6 nM) in obesity." (PMID 37002197, 2023). "Recent research suggests that leptin may be an important factor linking obesity, the MetS, and CCVD." (PMID 36984562, 2023). "The highest prevalence of monogenic obesity was seen in a highly consanguineous population of Pakistan in a study of obese children that investigated only 3 monogenic obesity genes (LEP, LEPR, and MC4R) and found around 30% of the cases carried pathogenic variants." (PMID 37329217, 2023). "However, leptin levels have been shown to increase in obesity, where patients develop resistance to this hormone." (PMID 37508717, 2023). "Administration of SL extract significantly decreased the leptin level, suggesting that SL extract may have a beneficial effect on obesity and cardiovascular risks." (PMID 36839173, 2023).
Obesity (continued). "In addition, we identified cut-off values for leptin in the assessment of obesity and insulin in the assessment of insulin resistance in patients with abnormal body weight." (PMID 37373485, 2023). "Since leptin and adiponectin modulate steroidogenesis, gonadotrophins release, and fertility, apelin replacement may improve reproductive dysfunction associated with obesity or T2DM through increasing adiponectin and the adiponectin/leptin ratio." (PMID 37424869, 2023). "The upregulated leptin in periodontitis with obesity might aggravate the progression of periodontitis and obesity via skewing proinflammatory M1 macrophage and stimulating proinflammatory cytokine expression in local periodontal ligament cells." (PMID 38069063, 2023). "Consequently, rapamycin-mediated lowering of serum leptin can be used as anti-leptin therapy in obesity-related pancreatic cancer." (PMID 37444627, 2023). "Nevertheless, the activity of systems exhibiting sustained leptin sensitivity with obesity, such as the HPT axis and SNA to the vascular beds of cardiovascularly relevant organs, decreases with weight loss, leading to resolution of hypertension and a decrease in TH levels." (PMID 36769012, 2023). "Adiponectin, leptin, and glucagon-like peptide-1 (GLP-1) are important hormones that regulate the metabolism and energy balance, and their dysregulation is associated with obesity and related metabolic disorders." (PMID 37176576, 2023). "Leptin has been proposed to be a link between obesity and cancers in various preclinical studies." (PMID 37378223, 2023). "Metformin has been reported as a Leptin sensitizer, enhancing the production of leptin receptors, which may contribute to improved leptin sensitivity and the reversal of obesity." (PMID 37860765, 2023). "Sun and colleagues reported that independent of obesity and leptin levels, there was a strong inverse association between high levels of circulating leptin SR and the risk for development of T2DM in American women." (PMID 36950695, 2023). "Interestingly, this strain does not develop central or peripheral leptin resistance, suggesting that increases in serum leptin is likely a compensation to hyperphagia-induced obesity." (PMID 37298724, 2023). "Recent studies have demonstrated that shorter sleep durations can promote peptide release and inhibit leptin release, leading to increased food intake, weight gain, decreased insulin sensitivity, and elevated blood glucose levels, ultimately contributing to obesity and impaired glucose tolerance." (PMID 37388641, 2023). "Moreover, ZnONPs have indirect mechanisms to alleviate cardiac pathology in obesity by reducing blood pressure, insulin resistance, dyslipidemia, and leptin level or restoring adiponectin concentration." (PMID 37749096, 2023). "Administration of GIP to high-fat-diet-treated mice increased blood levels of leptin, an anti-obesity hormone, while administration of tirzepatide in obese mice enhanced the influx of branched-chain amino acids into brown adipose tissue and stimulated thermogenic signaling." (PMID 37800161, 2023). "The immune system’s involvement in the adipose dysfunction and inflammation of obesity is well known and has been extensively reviewed; for example, leptin may be a key player in the adipose-immune system interactions." (PMID 37887382, 2023). "p < 0.01) and leptin (RYGB: 17.74 ± 10.08 ng/mL vs. obesity: 31.28 ± 8.86 ng/mL, adj." (PMID 37299461, 2023). "Third, obesity and BMI may influence the leptin level, higher leptin level was usually observed in obesity and high-BMI cases." (PMID 36914629, 2023). "Obesity is known to promote breast cancer progression through leptin and insulin signaling." (PMID 36732635, 2023). "In animal models, HFD-induced obesity reduced leptin sensitivity and increased food intake." (PMID 38136564, 2023). "IL-6 and the adipokine leptin are key mediators of inflammation in obesity." (PMID 37841878, 2023).